TPH2 (tryptophan hydroxylase 2)
Diseases named in the same sentence as TPH2 in open-access papers (continued):
Sharing a sentence is not in itself a finding about the gene and the disease.
depression (continued). "Moreover, on the population level, an intron variant, rs12229394, in the TPH-2 gene was found to be associated with depression and fatigue in women, and another synonymous variant, rs4290270, in exon 9 displayed a gender-dependent effect on depression susceptibility." (PMID 29952309, 2018). "In addition, the TPH-2 gene polymorphism have been found to be associated with late-onset depression, PTSD, suicide in patients with alcohol dependence and suicidal behavior, as well as with schizophrenia and panic in bipolar disorders in the Chinese Han population." (PMID 27871272, 2016). "Subsequent studies have also confirmed that Pet-1 participates in the transcriptional regulation of Tph2 and serotonin receptors, playing a multifaceted role in the development of depression." (PMID 40342516, 2025). "Pharmacological activation of TPH2 to promote serotonin synthesis is a key therapeutic strategy for improving depression." (PMID 41041075, 2025). "Our findings revealed significant differential expression of genes such as Oprm1, BDNF, Tph2, and Zfp769 in the depression mouse model (p < 0.05)." (PMID 40656047, 2025). "While the meta-analysis included healthy controls, other studies showing a link between TPH2 and suicide were compared between patients with depression, while one study involved only patients with bipolar disorder." (PMID 40282388, 2025). "The aim of this study was to investigate the association between the genetic type and alleles for the TPH1, TPH2, SLC6A4, HTR1A, HTR2A, and BDNF genes in Korean suicide attempters with major depressive disorder (suicide attempters) and a control group." (PMID 41300755, 2025). "In adolescents with depression in northern China, the Tph2 gene locus rs11178997 AT genotype is more common." (PMID 40342516, 2025). "Nevertheless, existing research is sufficient to establish Tph (particularly Tph2) as a critical molecule in the pathological mechanisms of depression." (PMID 40342516, 2025). "Homozygous TPH2 mice are prone to depression and usually show profound behavioral and neurological impairments, whereas stress-induced heterozygous TPH2 (HET) mice show cognitive impairment and signs of obsessive-compulsive disorder." (PMID 40182809, 2025). "In summary, brain SCFAs can activate ACSS2–PPARγ–TPH2 axis to play the antidepressive-like effects, and d-mannose is suggested to be an inducer of brain SCFAs in resisting depression." (PMID 38939042, 2024). "More recently, methylation of TPH2 gene has also been suggested as a biomarker for vulnerability to depression and antidepressant treatment outcome." (PMID 38802956, 2024). "They identified 9 CpG sites on the tryptophan hydroxylase-2 gene that differ significantly between patients with depression and healthy controls." (PMID 39028994, 2024). "High rates of severe depression were identified in PWH, who presented the rs4570625 TT and rs1386493 GG TPH2 polymorphic variants." (PMID 39768746, 2024). "As we observed that SCFAs can trigger ACSS2–PPARγ–TPH2 axis, the discovery of novel inducers of brain SCFAs is extremely important for treating depression." (PMID 38939042, 2024). "A decrease in the expression of TPH2, the rate-limiting enzyme for serotonin production, results in decreased serotonin synthesis, potentially triggering depression and a decline in mental status." (PMID 39475992, 2024). "The depression-related SNP (R439H) in the human Tph2 gene greatly diminishes 5-HT production, and chronic SSRI treatment exacerbates this depletion in humanized mouse carriers of R439H." (PMID 39748904, 2024). "On the basis of the baseline depression severity and TPH2 CpG sites, machine learning approaches can enhance our ability to predict the early-stage antidepressant response." (PMID 37127594, 2023). "On the basis of the baseline depression severity and the TPH2 CpG sites, machine learning approaches can enhance our ability to predict the early-stage antidepressant response." (PMID 37127594, 2023).
depression (continued). "Variants within the monoamine oxidase A (MAO-A, MAOA) and tryptophan hydroxylase 2 (TPH2) genes, the main enzymes in cerebral serotonin (5-HT) turnover, affect risk for depression." (PMID 37322010, 2023). "Comparison with the control group (1.96 ± 0.02), the reserpine-induced pain and depression model (0.87 ± 0.15) mice show significant decrease in brain cortex Tph2 mRNA level." (PMID 38259687, 2023). "Studies have reported that rs11178997, rs10879346, rs11179023, rs7305115, and rs120074175 in the TPH2 gene are all closely related to the occurrence of depression." (PMID 37161455, 2023). "The elevation of TPH2 mRNA expression in the raphe nuclei was reported to be involved in the emotional conditions, such as depression in mammals and avian species." (PMID 36909223, 2023). "Men with depression who experienced ELS had hypermethylation at the TPH2-5-203 CpG site, whereas depressed women who experienced ELS had hypermethylation at the TPH2-10-60 CpG site." (PMID 35865627, 2022). "In this study, we found that Ahi1, a protein associated with susceptibility to depression, regulated serotonin production through the GR/ERβ/TPH2 pathway, indicating a critical role for Ahi1 in the regulation of depression." (PMID 35643536, 2022). "For instance, a close connection between diminished TPH2 activity and depression has been detected based on single nucleotide polymorphisms (SNPs)." (PMID 34625528, 2021). "The next important enzymes associated with depression are tryptophan hydroxylase 1 and 2 (TPH1, TPH2)." (PMID 32406039, 2020). "Variations in TPH2 genetic transcripts and expressions have also been linked to a number of disorders including PTSD, depression, and panic attacks." (PMID 33178100, 2020). "Expression of the key enzyme in the Trp-5-HT pathway, TPH2, is inhibited in depressive rat model, and brain 5-HT synthesis is decreased in depression patients." (PMID 31534466, 2019). "The association between depression and haplotypes of the studied polymorphisms of the TPH1 or TPH2 genes was also assessed." (PMID 29314569, 2018). "To fill this knowledge gap, we tested the hypothesis that the TPH-2 gene exonic variant rs4290270 may be a susceptibility locus for primary insomnia in Han Chinese and further hypothesized that this variant was associated with depression symptoms in patients with primary insomnia." (PMID 29952309, 2018). "An increase by seven times of the risk of depression was confirmed for the A/A‐C/A combined genotypes of c.‐1668T>A—TPH1 (rs623580) and c.‐1449C>A—TPH2 (rs7963803) (P = 0.011)." (PMID 29314569, 2018). "The location and function of TPH2 has made it an essential candidate gene in many mental disorders, including depression." (PMID 28968985, 2017). "Locomotor activity and anxiety- and depression-like behavior as well as conditioned fear responses were differentially affected by Tph2 genotype, sex, and CMS." (PMID 25716307, 2015). "Tph2 null mutants (Tph2−/−) displayed increased general metabolism, marginally reduced anxiety- and depression-like behavior but strikingly increased conditioned fear responses." (PMID 25716307, 2015). "The second study will assume compensatory TPH2 activities for major depression through cerebrospinal fluid (CSF) levels of the 5-HT metabolite, 5-hydroxyindoleacetic acid." (PMID 25540092, 2014). "We first detected the anxiety- and depression-like behaviors in PC/Tph2 mice (Pet1-Cre;Tph2flox/flox) in which Tph2, the key enzyme for 5-HT synthesis, was deleted in the central serotonergic neurons." (PMID 25294992, 2014). "Among these key enzymes, only TPH2 activation (led by feedback from 5-HT depletion) provides alleviation from depression, partially compensated for by 5-HT synthesis." (PMID 25540092, 2014). "Tph2-/- mice have also been reported to have altered behaviors such as increased conditioned fear responses, aggression, depression-like behaviors, and impairment of maternal care." (PMID 23935583, 2013).
depression (continued). "Genetic evidence also supports a role for polymorphisms in genes encoding SERT or the rate-limiting enzyme for brain 5-HT synthesis, tryptophan hydroxylase 2 (TPH2), in depression." (PMID 22826345, 2012). "Further, we had no the detail mechanistic explanation regarding the role of serotonin functioning in depression for TPH2 SNP." (PMID 20738857, 2010). "TPH2 (Q8IWU9) is known to be involved in major depressive disorder (MIM:608516) and is directly involved in the biosynthesis of serotonin from L-tryptophan." (PMID 20532224, 2010). "Furthermore, Vmat expression in the dorsolateral PFC shows sex differences; male depression patients exhibit lower expressions of both Vmat1 and Vmat2, whereas female depression patients show higher expression of Vmat2 and Tph2." (PMID 40342516, 2025). "In our study, the volunteers with depression were also taking antidepressant medication, which might increase the abundance of genera strongly correlated with TPH2, such as Bilophila." (PMID 37007475, 2023). "Therefore, the identification of the key protein that simultaneously controls both BDNF and TPH2 is important for the treatment of depression." (PMID 37914710, 2023). "Interestingly, the TPH2 rs78162420 AC genotype has been correlated with a higher probability of depression in PD patients." (PMID 37374342, 2023). "In addition, E2 levels in the blood and brain of male and female mice were measured to investigate the effect on the ERβ/TPH2 pathway and to reveal the mechanisms for the phenomenon of gender differences in depression-like behaviors." (PMID 35643536, 2022). "In the present study, western blot, gene knockdown, immunofluorescence, dual-luciferase reporter assay, and rescue assay were used to detect changes in the Ahi1/GR/ERβ/TPH2 pathway in the brains of male stressed mice and male Ahi1 KO mice to explain the pathogenesis of depression-like behaviors." (PMID 35643536, 2022). "Increasing evidence indicates that TPH2 is related to MDD in depression." (PMID 35643536, 2022). "5-HT2A function has not been strongly associated with depression or anxiety, although co-occurring polymorphisms in the serotonin synthesis enzyme TPH2 and 5-HT2A do correlate with MDD." (PMID 35280519, 2021). "Furthermore, although our results are suggestive, further research will be needed on the possibility of employing pIRES-hrGFP-1a-Tph2-FLAG as a treatment for psychiatric diseases (e.g., major depression) involving a Tph2 dysfunction." (PMID 34625528, 2021). "Another important function of VD interferes with the synthesis of serotonin by the expression of serotonin‐synthesizing gene tryptophan hydroxylase 1 and tryptophan hydroxylase 2, and VD may thus prevent depression by maintaining normal serotonin levels." (PMID 32945627, 2020). "Up-regulation of TPH2 induced by chronic Flx treatment appeared to correlate to its antidepressant effects, thus TPH2 up-regulation may be a counter depression measure." (PMID 30003515, 2019). "Additionally, molecular biomarkers of depression (expression of Fkbp5 and Tph2) were studied in hippocampus." (PMID 30533439, 2018). "Interestingly, contradictory findings regarding the assessment of depression-like behavior of Tph2 knock-out mice have been generated." (PMID 30087403, 2018). "The Tph2 gene may be a reliable biomarker for major depression because the levels of TPH2 mRNA and protein expression were consistently found to be elevated in depressed suicide victims." (PMID 30533439, 2018). "Haplotype linkage of TPH2 to SB, major depression, borderline disorder, and cerebrospinal fluid 5-hydroxyindoleacetic acid (a possible mediating phenotype) provides preliminary evidence that there is a functional locus that is potentially within a haplotype block of at least 52 kb in size." (PMID 27721799, 2016).
depression (continued). "Important observations were also made using three genetically modified mouse models, all characterized by altered behaviors in depression-related paradigms, but demonstrated qualitative differences (significant decreases or increases) in tph2 mRNA expression in the DRN." (PMID 26624017, 2015). "Conversely, there are also TPH2 abnormalities in depression." (PMID 25540092, 2014). "We also used a case-control study design in the same individuals to investigate a possible association with a susceptibility to depression of the SNPs of five other serotoninergic system genes: 5HTR2A (SNP 6313), 5HTR1B (SNP 6296), HTR2C (SNP6318), TPH1 (SNP 1800532), and TPH2 (SNP 7305115)." (PMID 22619623, 2012). "Among these, MAOA, COMT, TPH1, and TPH2 have been reported to be associated with depression, but a recent genome-wide association study found no significant genome-wide association, and the best candidates did not involve these pathways." (PMID 21827647, 2011). "A total of 430 unrelated, major depression patients with and without suicide behaviors were genotyped for the TPH2 rs7305115 polymorphisms." (PMID 20738857, 2010). "Other studies have found increased tph2 mRNA and protein expression in the caudal part of the DR in persons with depression who died by suicide, while in alcohol-dependent persons with depression who died by suicide, increases in TPH2 protein are restricted to the cDRD region." (PMID 38705984, 2024). "For example, six SNPs in the tryptophan hydroxylase gene (TPH1, TPH2) have been studied to verify the association between polymorphisms in the TPH and the development of depression, and the tryptophan hydroxylase pathway is implicated in the pathogenesis of depression." (PMID 37581520, 2024). "Moreover, as an important monoamine neurotransmitter, 5-HT is produced through the rate-limiting enzyme Tryptophan hydroxylase 2 enzyme (TpH2) in the brain, and abnormalities in different processes of serotonergic activity might initiate depression." (PMID 37033659, 2023). "Sex differences in brain estrogen levels may at least partially account for the differences in depressive behaviors between male and female Ahi1 KO mice, indicating that Ahi1 regulates serotonin production by the GR/ERβ/TPH2 pathway involving sexual differences in depression-like behaviors." (PMID 35643536, 2022). "Therefore, Ahi1 regulates serotonin production by the GR/ERβ/TPH2 pathway involving sex differences in depression-like behaviors; our findings may facilitate finding personalized treatments for patients with MDD." (PMID 35643536, 2022). "The C/A‐C/A and A/A‐C/A combined genotypes of the c.803+221C>A—TPH1 and c.‐1449C>A—TPH2 (rs1800532 versus rs7963803) may lead to a development of depression, and the C/A‐C/C combined genotype of the same SNPs combination reduce the risk of developing the disease." (PMID 29314569, 2018). "However, the association of the TPH-2 gene with depression in patients with primary insomnia has not yet been reported in the medical literature." (PMID 29952309, 2018). "Because the TPH2 gene is associated with depression in subjects without stroke one may argue that our findings are not specific to PSD." (PMID 29484259, 2018). "Moreover, it is believed that the hereditary or acquired involvement of tryptophan hydroxylase 2 (Tph2) or 5-hydroxytryptamine transporter (5-HTT) is responsible for the reduced concentration of serotonin in the central nervous system, causing depression and affective disorders." (PMID 21450092, 2011). "Korean red ginseng increased TPH2 and TPH1 in the hippocampus of a rat model of prolonged stress and ameliorated depression-like behavior." (PMID 40243512, 2025). "Estrogen increases the expression of TPH2, TH, and SLC6A4, downregulates MAO and the 5-HT1A receptor and presents antidepressant-like effects in female patients with depression." (PMID 40243512, 2025).
depression (continued). "Analysis of transcriptomic data from depression-related mouse models in the GEO database enabled the identification of key genes, including Oprm1, BDNF, and Tph2, which exhibited marked expression differences between the NAC and PFC regions." (PMID 40656047, 2025). "The reduction in depression-like behavior at the juvenile stage could be an early effect of this serotonin deficiency in rats that consumed ASP; supporting this, a reduction in anxiety-like behavior is one of the main behavioral changes in a serotonin-deficient mouse model (Tph2 knock-out)." (PMID 38398814, 2024). "Recently, we reported dysregulation in the TPH2 gene after the administration of oral chronic EFV within the brainstem, hypothalamus, and amygdala and depression-related processes in behavior trials in mice." (PMID 39768746, 2024). "Consistent with this, TPH2 overexpression in DRN5-HT neurons alleviated the damage of synaptic function in 5×FAD mice and attenuated the early depression and cognitive impairments." (PMID 39044270, 2024). "Cereulide arouses depression in different animal species by inhibiting the production of tryptophan hydroxylase 1 and 2 (TPH-1 and TPH-2), key enzymes for the precursor of serotonin (5-HT) synthesis, which controls depression behavior." (PMID 36832907, 2023). "In addition, Tph2-deficient mice do not have increased anxiety-like or depression-like behaviors." (PMID 28713247, 2017). "The response to SSRIs is abolished in a subset of Tph2 KO mice, thus showing that the antidepressant effects of SSRIs indeed partially depend on an intact 5-HT system, but central 5-HT deficiency is not a prerequisite in the onset of depression-like behaviors, at least in mice." (PMID 28713247, 2017). "Potentially, all types of depression can be expressed through combinations of these key enzymes using a matrix with peripheral (TPH1, TDO, IDO) and central (TPH2, KMO) determinants." (PMID 25540092, 2014). "For example, the TPH2−/− and TPH2-R439H mutant that reduce or eliminate 5-HT show depression phenotypes." (PMID 24936175, 2014). "Additional examples include schizophrenia for RELN, GluR6, GRIN2A, GRIN2B, and CNTNAP2, childhood absence epilepsy for GABRB3, ADHD and depression for 5-HTT, and major depression for TPH2." (PMID 23935565, 2013). "The traditional Chinese medicine Aurantii Fructus Immaturus-Carbonisata has demonstrated significant antidepressant effects by upregulating Tph2 expression in the cortex of mice, thereby reducing immobility time in both the CUMS model and the reserpine-induced pain-depression dyad model." (PMID 40342516, 2025). "Trp, a neurotransmitter precursor, is known to accelerate depression, which led us to hypothesize that MGO-induced depression in mice may be mediated by modulating the levels of Trp and related factors such as 5-HTP, 5-HT, TPH1, and TPH2." (PMID 39574138, 2024). "The down-regulation of TPH2 expression decreases 5-HT levels in 5×FAD mice and promotes depression." (PMID 39044270, 2024). "In the pain-depression dyad model, the AFIC-CDs groups decreased the immobile time, showed effect in increasing both the neurotransmitters’ levels and the expression of mRNA of BDNF and Tph2, and decreased the IL-1β and TNF-α levels in mouse brain cortex." (PMID 38259687, 2023). "TPH-2 knock-in mice, which show a decrease in brain 5-HT by ∼70%, do not show depression-like behavior without social defeat stress either." (PMID 37813564, 2023). "Currently, the only research in the literature regarding the acetylation of aromatic amino acid metabolic enzymes is about the acetylation of tryptophan hydroxylase 2 (TPH2), which has been reported to be involved in prenatal stress-induced depression-like behavior in male juvenile offspring rats." (PMID 32283695, 2020).